GSX2 (GS homeobox 2)
Description:
Transcription factor that binds 5'-CNAATTAG-3' DNA sequence and regulates the expression of numerous genes including genes important for brain development. During telencephalic development, causes ventralization of pallial progenitors and, depending on the developmental stage, specifies different neuronal fates. At early stages, necessary and sufficient to correctly specify the ventral lateral ganglionic eminence (LGE) and its major derivatives, the striatal projection neurons. At later stages, may specify LGE progenitors toward dorsal LGE fates, including olfactory bulb interneurons (By similarity).
Synonyms: GSH2; DMJDS2
Tractability: No criterion of Open Targets' tractability assessment is met for any kind of drug.
Gene: Protein-coding gene on chromosome 4 (54,099,523 to 54,102,498, forward strand). Ensembl gene ENSG00000180613.
Subcellular location: Nucleus; Cytoplasm
Gene Ontology:
Molecular function: DNA-binding transcription factor activity, RNA polymerase II-specific; sequence-specific double-stranded DNA binding; DNA binding; DNA-binding transcription factor activity
Biological process: generation of neurons; olfactory bulb development; regulation of DNA-templated transcription; regulation of transcription by RNA polymerase II
Cellular component: cytoplasm; nucleus; chromatin
Genetic constraint (gnomAD): Loss-of-function variants: 13 observed, 16.16 expected, observed/expected ratio (o/e) 0.8, 90% interval 0.52 to 1.28. The upper end of that interval is the gene's LOEUF score, 1.28, which puts it in group 5 of 6, group 1 being the genes least tolerant of losing a copy. Missense variants: 377 observed, 329.2 expected, observed/expected ratio (o/e) 1.15, 90% interval 1.05 to 1.25. Synonymous variants: 177 observed, 143.46 expected, observed/expected ratio (o/e) 1.23, 90% interval 1.09 to 1.4.
Gene-disease validity (ClinGen):
ClinGen rates the evidence that GSX2 causes each of these diseases.
diencephalic-mesencephalic junction dysplasia syndrome 2 (autosomal recessive): Moderate.
Homologues: Orthologues: chimpanzee GSX2 (99% identical), macaque GSX2 (97% identical), dog GSX2 (94% identical), pig GSX2 (94% identical), rat Gsx2 (89% identical), mouse Gsx2 (89% identical), guinea pig GSX2 (88% identical), rabbit GSX2 (86% identical), tropical clawed frog gsx2 (59% identical), zebrafish gsx2 (59% identical), Drosophila melanogaster zen (23% identical), Drosophila melanogaster CG30480 (21% identical), and 1 more. Paralogues in human: PDX1 (25% identical), HOXD3 (23% identical), HOXA3 (23% identical), HOXB3 (22% identical), HOXA4 (21% identical), HOXC9 (21% identical), HOXD4 (21% identical), HOXA2 (20% identical), HOXB4 (20% identical), HOXC4 (20% identical), HOXB2 (20% identical), HOXD9 (20% identical), and 30 more.
Diseases named in the same sentence as GSX2 in open-access papers:
GSX2 is named in the same sentence as 10 diseases in open-access papers, as found by Europe PMC text mining. Sharing a sentence is not in itself a finding about the gene and the disease. The quoted sentences say what the papers report.
glioma (4 papers, 2023 to 2025). A benign or malignant brain and spinal cord tumor that arises from glial cells (astrocytes, oligodendrocytes, ependymal cells). "Diffuse hemispheric glioma, H3 G34-mutant were recently demonstrated as developing from GSX2-expressing interneuron progenitor-like cells from the SVZ but, to our knowledge, data is lacking for other pHGG subtypes." (PMID 37328883, 2023).
pancreatic cancer (1 paper, 2024). "A study shows that the silencing of GSX2 in pancreatic cancer cells resulted in a decrease in their proliferation, migration, and invasion, along with an increase in apoptosis and enhanced sensitivity to gemcitabine treatment." (PMID 39457550, 2024).
tumor (3 papers, 2019 to 2025). "NB-FOXR2 tumors are not the only tumor type to be associated to a cortical interneuron lineage; H3.3G34R/V HGGs originate in GSX2+ interneuron progenitors, and the chromatin state at the GSX2 locus in this cell context underlies the vulnerability to PDGFRA alterations." (PMID 39495206, 2025).
GSX2 also shares sentences with these, for which no sentence is quoted: infection (2 papers); Anxiety (1); cancer (1); myeloid malignancies (1); nematode infection (1); respiratory failure (1); thyroid cancer (1).